APP (amyloid beta precursor protein)
Diseases named in the same sentence as APP in open-access papers (continued):
Sharing a sentence is not in itself a finding about the gene and the disease.
COVID-19 (24 papers, 2020 to 2024). A disease caused by infection with severe acute respiratory syndrome coronavirus 2. "The activation of intracellular signaling transduction pathways associated with APP/Aβ and tau pathologies represents an additional relevant commonality, putting in mutual relation the occurrence of COVID-19 and AD." (PMID 37998336, 2023). "Our findings provide experimental evidence to interpret APP-related mechanisms underlying AD-like neuropathology in COVID-19 patients and may pave the way to help inform risk management and therapeutic strategies against diseases accordingly." (PMID 38104129, 2023). "Although a significant increase in APP deposits was evident in acute COVID-19 cases, only individual patients in the post-COVID cohort exhibited deposits without reaching statistical significance for this group." (PMID 39060438, 2024). "The RNA-seq analysis of COVID-19 positive patients’ blood samples in comparison to COVID-19 negative patients’ blood samples in the US exhibited a significant increase in APP transcription." (PMID 35163117, 2022). "Further, a study on a single-cell RNA-seq from post-mortem brain tissues of COVID-19 patients discovered that APP was one of the most upregulated genes in oligodendrocytes." (PMID 35163117, 2022). "In response to the health crisis caused by COVID-19 worldwide, this study seeks to investigate the impact of SARS-CoV-2 upstream regulators on ACE2 and the consequent change in APP expression." (PMID 35163117, 2022). "Following studies of inflammation caused by coronavirus-2019 (COVID-19) infection, this study investigated the impact of COVID-19 on APP expression." (PMID 35163117, 2022). "Surprisingly, several recent multi-omic analyses of samples from COVID-19 patients have revealed a potential relationship between COVID-19 and APP metabolism." (PMID 33941272, 2021). "For example, RNA-seq analysis has demonstrated a significant increase of APP transcript in the blood samples from COVID-19-positive patients, compared with COVID-19-negative ones in the United States." (PMID 33941272, 2021). "It has been reported that in APP/PS1 transgenic mice, the S2 subunit of the SARS-CoV-2 S protein can interact with the γ-secretase complex, enhancing γ-secretase cleavage of APP to accelerate the production of Aβ, thereby promoting the emergence of COVID-19 neuropathological changes." (PMID 37962454, 2024). "A more complex interaction between APP and viral infection has been reported in COVID-19." (PMID 37962454, 2024). "Notably, the multi-group analysis of COVID-19 patient samples shows that there is a potential relationship between the metabolic process of APP and COVID-19 infection." (PMID 37009449, 2023). "In conclusion, we have identified APP as a receptor protein for nerve cells and revealed a previously unknown mechanistic insight into COVID-19-related neuropathological sequelae." (PMID 38104129, 2023). "Additionally, there is a potential relationship between COVID-19 and APP metabolism, which has been revealed by several recent multi-omic sample analyses from COVID-19 patients." (PMID 35163117, 2022). "Furthermore, a single-cell RNA-seq study carried out by Yang and colleagues has identified APP as one of the most up-regulated genes in oligodendrocytes isolated from the post-mortem brain tissues of COVID-19 patients." (PMID 33941272, 2021). "The underlying mechanisms of the pathogenesis and infection of S-COVID-19 could be better described by suggesting APP, EGF, C3, APOE, and APOA1 as the novel chief organizers of the network foundation." (PMID 33244380, 2020). "Therefore, the effect of COVID-19 on APP metabolism still needs further exploration." (PMID 37009449, 2023). "Therefore, changes in APP levels in urine samples of severe COVID-19 patients may justify the possible relationship between the virus and APP accumulations and, consequently, its linkage with neurodegenerative diseases." (PMID 33244380, 2020).
COVID-19 (continued). "Plasma proteins including AAT, ABO, APP, FGA, HPX, ITIH4, PON and others showed similar or higher observation frequency in NHP compared to COVID-19." (PMID 37031181, 2023). "Another study conducted RNA-seq analysis of COVID-19 patients and found a significant increase in amyloid-beta precursor protein (APP) expression compared to non-infected patients." (PMID 35163117, 2022). "The analysis of COVID-19 extended interactome indicates several membrane bound gene/proteins (i.e., ICAM1, EGFR, ERBB2, APP, ADR2, FAS, CDH1, and MAPT), whose activity and/or expression could be affected by SARS-CoV-2 challenge." (PMID 33123533, 2020). "Post-mortem indications for axonal injury (including positive APP staining) have also been described in three cases with a recent COVID-19 infection, but we did not observe other acute pathologies related to COVID-19, such as hemorrhagic lesions or microvascular injury." (PMID 37161501, 2023). "However, it is worth noting that the dysregulation of APP metabolism-related genes in COVID-19 patients is not constantly observed among multi-omic studies." (PMID 33941272, 2021). "Moreover, dysregulation of APP and APOA1 could both contribute to the possible adverse effects of COVID-19 on the nervous system." (PMID 33244380, 2020). "Thus, whether or not COVID-19 influences APP metabolism remains an open question that needs to be addressed in the future." (PMID 33941272, 2021).
prion disease (24 papers, 2009 to 2025). A transmissible disease that is caused by a protein that is able to induce abnormal folding of normal cellular proteins, leading to characteristic spongiform brain changes, which are associated with neuronal loss without an inflammatory response. "The Reelin signaling pathway, implicated both in Alzheimer’s and prion diseases, engages Dab1, an adaptor protein influencing APP processing and amyloid beta deposition." (PMID 40733546, 2025). "We compare diseases caused by misfolding and aggregation of APP-derived Aβ peptides, tau, and α-synuclein with PrP prion disorders and argue for the classification of NDs caused by misfolding of these proteins as prion diseases." (PMID 34064393, 2021). "Our findings are in apparent conflict with a prior study that reported prion inoculation of Tg2576 APP transgenic mice accelerated both Aβ deposition and prion disease." (PMID 29142106, 2017). "Tg44 mice also show high amounts of APP co-localizing with PrPres suggesting axonal dystrophy, and they have prominent vacuolation of white matter, but not gray matter, suggesting a different type of brain damage than seen in typical prion disease." (PMID 24447368, 2014). "APP and PrP are both cell-surface proteins residing in cholesterol-rich lipid rafts of the cell membrane and play an important role in the development of AD and prion diseases, respectively." (PMID 22897917, 2012). "Although the role of the Reelin signaling cascade in prion diseases has not been deeply investigated, it has been reported that APP processing and β-amyloid deposition in sporadic Creutzfeldt-Jakob disease (CJD) patients are dependent on Dab1." (PMID 40733546, 2025). "IL-34 and Syndecan-1 also increased in APP cKO, especially at 6 months of age, and IL34 was recently proposed to be the main brain factor to stimulate proliferation of microglia in the ME7 model of prion disease." (PMID 33402196, 2021). "Even though we have found that cerebral Aβ deposition can be induced in mice that do not overexpress APP, the likelihood of cases of AD occurring due to exposure to exogenous Aβ aggregates, similar to what occasionally occurs in prion disease, is improbable." (PMID 29615128, 2018). "However, as the processing of APP by BACE1 is a key step for the production of Aβ peptides, and AICD in turn up-regulates PrP expression, increased levels of BACE1 could be related to higher cellular levels of PrP that are associated with increased susceptibility to prion diseases." (PMID 22952813, 2012). "In terms of the acceleration of prion disease in Tg2576 mice, it is interesting to note that deleting PrPC expression in Tg2576 results in only a partial rescue of cognitive performance as opposed to the complete recovery seen in other APP transgenic lines." (PMID 29142106, 2017).
type 2 diabetes (23 papers, 2010 to 2025). "A rat model of type II diabetes reveals cortical neuron loss and increased soluble amyloid precursor protein (APP) and phospho-Tau." (PMID 26161852, 2015). "Type 2 diabetes-induced neurodegeneration in rats revealed a significant upregulation of gene expression of APP and BACE-1 when compared with control rats (p < 0.01)." (PMID 34834352, 2021). "Here in the present study, we showed that metformin, the most widely used drug for type 2 diabetes, suppressed Cdk5 hyper-activation and Cdk5-dependent tau hyper-phosphorylation in the APP/PS1 mouse hippocampus." (PMID 32670025, 2020). "Rat models of type 2 diabetes mellitus (T2DM) induced by streptozotocin (STZ) have increased dystrophic neurites together with aggregation of APP, phosphorylated tau and Aβ, mimicking AD symptoms." (PMID 34689261, 2022). "Examples include glycogen synthase (type II diabetes), NFkB/CBP transcription (inflammation), AP-1/NFAT (cardiac hypertrophy), and Tau/APP (neurological disorders) as well as Wnt and Notch signaling (bone homeostasis and vascular calcification and cancer)." (PMID 35923616, 2022). "The expression of APP and tau mRNAs by RT-PCR in normal and type 2 diabetes pancreas and in insulinoma beta cells (INS), as well as the detection of APP and tau immunoreactive bands by Western blot, indicates that APP and tau are present in the pancreatic tissue and in islet beta cells." (PMID 26961231, 2016).
viral infection (23 papers, 2012 to 2026). "We created an AD mouse to address the need to develop an small animal model that allows studies of viral infection by making a knock-in (KI) with the human amyloid precursor protein (APP)KM670,671NL Swedish mutation to the mouse genome." (PMID 40309515, 2025). "While the APP's role in AD pathogenesis has been well established, its broader physiological functions, particularly in the context of viral infections such as HIV-1, remain poorly understood." (PMID 42012178, 2026). "Emerging data even implicate both APP and ⍺Syn in immune regulation, with APP showing antimicrobial activity and ⍺Syn involved in the resistance to neurotropic viral infections." (PMID 38041542, 2025). "The qPCR analysis indicated that Clec5a mRNA levels were higher in APP transgenic mice than WT mice, resembling the response observed following viral infection." (PMID 39443966, 2024). "The amyloid precursor protein (APP) pathway was significantly upregulated in the kidneys and bursa following viral infection." (PMID 38743760, 2024). "The in vitro impacts of APP overexpression on virus infection were further evaluated in HEK293T/ACE2 cells, SH-SY5Y cells, and Vero cells." (PMID 38104129, 2023). "be infected with SARS-CoV-2 pseudovirus, in which knockdown APP expression decreased the virus infection." (PMID 38104129, 2023). "The scFv constructs were expressed in hepatic cells in an APP/PS1 AD mouse model by viral infection using a rAAV as a vector." (PMID 33376140, 2021). "The abundance variation of APP following virus infections has been recently reported." (PMID 23874584, 2013). "Thus, reduced expression of both DUSP26 and APBB2 could potentially amplify dysregulation in APP trafficking, oxidative stress, and cell death signaling in response to viral infection or hypoxia-related stress." (PMID 40733561, 2025). "Processing of APP may be influenced by viral infections, specifically by HSV-1." (PMID 38535583, 2024). "Genetic analysis identified copy number variations (CNVs) in the APP, PSEN1, PSEN2, MAPT, and GRN genes, while viral infections (HSV-1, HSV-2, CMV, EBV, HIV, SARS-CoV-2, Hepatitis A, B, and C) and vitamin D, B12, and B9 deficiencies were measured." (PMID 40725212, 2025). "For example, upregulated levels of APP, BIN1, and INPP5D are connected with increases AD risks but play inhibitory roles in some viral infections." (PMID 37962454, 2024). "Because Cre virus infection rate of neurons was close to 100%, the remaining APP protein is likely derived from cocultured nonmutant glia." (PMID 36260691, 2022). "Taken together, we demonstrate that respiratory viral infection in the AD mouse model leads to elevated amyloid-β plaque load in the hippocampus and also induces a chronic increase in the activation status of microglia, which was not the case for non-infected APP/PS1 animals." (PMID 33994946, 2021).
colon carcinoma (21 papers, 2011 to 2025). "Using a colitis-associated colorectal cancer model, APP mutations promoted colon tumor formation in male mice but inhibited it in female mice." (PMID 41279101, 2025). "The APP pathway is also closely linked to the progression of various cancers, including lung cancer, pancreatic cancer, and colon cancer." (PMID 39936154, 2024). "Prolonged discharging of ER Ca2+ stores was also detected in APP-deficient T84 human colon carcinoma cell line, using cyclopiazonic acid to inhibit the SERCA." (PMID 36768625, 2023). "The gene that encodes APP is part of a genetic signature for increased likelihood of metastasis in patients with early stage mismatch-repair proficient sporadic colon cancer." (PMID 26840089, 2016). "Despite the intriguing associations between APP biology and cancer progression, the underlying mechanisms, particularly those detailing sex-specific differences in disease progression and APP metabolism in the context of colon cancer, remain largely unexplored." (PMID 41279101, 2025). "We confirmed APP expression in both normal colons and human colon cancers across various grades of differentiation." (PMID 41279101, 2025). "The majority of studies have shown an elevated expression of APP in several types of tumors, including breast, pancreatic, prostate, and colon cancer, promoting cellular growth and proliferation." (PMID 39123408, 2024). "Recent studies indicate that both CBZ and VPA exhibit anticancer effects by reducing APP levels in human colon cancer cells." (PMID 39123408, 2024). "Both in vitro and in vivo studies have demonstrated the roles of APP in promoting colon cancer growth and proliferation." (PMID 35875068, 2022). "Several reports have shown that sAPPα, comprising almost the entire extracellular region of APP, has mitogenic effects in fibroblasts, pancreatic, and colon cancers." (PMID 36142659, 2022). "Both in vitro and in vivo studies have shown that APP promotes growth and proliferation of colon cancer." (PMID 26840089, 2016). "We first investigated the expression levels of APP in human colon cancer." (PMID 41279101, 2025). "To understand why AOM/DSS treatment resulted in differential phenotypic outcomes in an APP mutant background at the molecular level, we conducted RNA-seq using colon cancer tissues, adjacent normal colon tissues, or normal colon tissues when tumors were not formed." (PMID 41279101, 2025). "In addition, APP has been shown to regulate proliferation through the ERK signaling pathway in colon cancer." (PMID 35678671, 2022). "Moreover, the administration of conditioned media from parental cells or of sAPP can rescue proliferation of APP-silenced breast or colon cancer cells." (PMID 33926496, 2021). "APP concentration with the treatment of CBZ in human colon cancer diminished." (PMID 34066808, 2021). "Notably, APP appears to play a crucial role on proliferation of tumor cells also in breast and colon cancer." (PMID 33926496, 2021). "Moreover, treating pancreatic and colon cancer cells with VPA leads to inhibition of tumor cell growth by down-regulation of β-amyloid precursor protein (APP) and secreted soluble APPα." (PMID 31370819, 2019). "Another study revealed an APP overexpression in human pancreatic and colon cancer." (PMID 23662100, 2013). "Consistent with the findings obtained in studies of APP, knock-down of APLP2 reduced proliferation of the Caco2 colon cancer cell line." (PMID 26840089, 2016). "Recent studies have also reported that amyloid precursor protein (APP) is upregulated in pancreatic cancer cells and SW837 colon carcinoma cells both in vitro and in vivo." (PMID 22084729, 2011).
colon carcinoma (continued). "Finally, the PBS solution containing FePSe3@APP was mixed with mouse colon cancer cell membrane vesicles (CT26 CCM) and the nano-biomimetic material FePSe3@APP@CCM NSs were obtained by extrusion." (PMID 37403095, 2023). "In human colon cancer, VPA treatment was found to reduce APP concentration." (PMID 34066808, 2021).